CFTR (CF transmembrane conductance regulator)
Diseases named in the same sentence as CFTR in open-access papers (continued):
Sharing a sentence is not in itself a finding about the gene and the disease.
prostatitis (4 papers, 2010 to 2025). An infectious or non-infectious inflammatory process affecting the prostate gland. "Declines in both ARSB and in CFTR have been associated with the development of malignancies, including prostate malignancy." (PMID 40362587, 2025). "The present results have provided the molecular mechanism underlying the long observed pH increase in prostatitis and demonstrated a previously unsuspected role of CFTR in the host defense of the prostate." (PMID 21151921, 2010). "Since HCO3− has been implicated in bacterial killing, the enhanced CFTR-mediated HCO3− secretion in prostatitis may serve as a host defense mechanism." (PMID 21151921, 2010). "In response to bacterial infection, prostatitis exhibits enhanced bicarbonate secretion involving CFTR, resulting in an elevation of pH." (PMID 38258089, 2024). "Since bicarbonate has been shown to be involved in antibacterial activity, the reinforced CFTR-mediated bicarbonate secretion in prostatitis can function as a host defense mechanism." (PMID 38258089, 2024). "In summary, the present study has elucidated the molecular mechanism underlying the long observed but unexplained characteristic alkaline shift in pH in prostatitis and revealed a previously undefined role of CFTR in host defense against bacterial infection in the prostate." (PMID 21151921, 2010). "While both in vitro and in vivo experiments on rat prostate epithelial cells strongly indicated that the CFTR-mediated HCO3− secretion is enhanced in prostatitis, which has bactericidal capacity, it remains to be confirmed that this host defense mechanism is also present in human prostate." (PMID 21151921, 2010). "We further hypothesized that the enhanced CFTR-mediated HCO3− secretion in prostatitis might be an important host defense mechanism of the prostate against bacterial infection." (PMID 21151921, 2010). "The present findings may have implications beyond prostatitis since CFTR is expressed in a wide variety of tissues where bacterial infections are readily contracted." (PMID 21151921, 2010). "Taken together, we hypothesized that CFTR might be involved in prostatic HCO3− secretion, its upregulation by inflammatory cytokines and thus enhanced HCO3− secretion might be responsible for the hallmark increase in pH observed in prostatitis." (PMID 21151921, 2010). "What is the physiological significance of the upregulation of CFTR and the possible enhanced CFTR-mediated prostatic HCO3− secretion during prostatitis?" (PMID 21151921, 2010). "The relevance of the CFTR-mediated HCO3− secretion in humans was demonstrated by the upregulated expression of CFTR and CAII in human prostatitis tissues." (PMID 21151921, 2010). "This suggests that a physiological consequence to bacterial infection or LPS challenge in the prostate would be the enhancement of the CFTR-mediated HCO3− secretion, which may be responsible for the increase in pH observed in prostatitis." (PMID 21151921, 2010). "In order to investigate the role of CFTR in prostatitis, we first examined its expression in rat prostate since CFTR expression in the prostate has not been demonstrated in any species other than the human." (PMID 21151921, 2010). "The CFTR and its mediated HCO3− secretion may be up-regulated in prostatitis as a host defense mechanism." (PMID 21151921, 2010). "Compared to the tissue without inflammation, the expression of CFTR in the prostate glands evident of lymphocytes infiltration was much stronger, indicating that the expression of CFTR was up-regulated in human prostatitis." (PMID 21151921, 2010). "The upregulation of both CFTR and CAII in the inflamed human prostate tissues indicate that the CFTR-mediated HCO3− secretion may also be enhanced upon inflammation, which may be responsible for the high pH observed in human prostatitis." (PMID 21151921, 2010).
prostatitis (continued). "Since increased levels of inflammatory cytokines including IL-1β and TNF-α are also found in prostatitis, with or without bacterial infection, they may also up regulate CFTR in the prostate, thereby enhancing HCO3− secretion and leading to the characteristic pH increase in prostatitis." (PMID 21151921, 2010).
renal agenesis (4 papers, 2016 to 2025). Renal agenesis (RA) is a form of renal tract malformation characterized by the complete absence of development of one or both kidneys (unilateral RA or bilateral RA respectively), accompanied by absent ureter(s). "In CFTR-related anomalies, kidney development is usually preserved, with unilateral renal agenesis observed in only ~11% of CBAVD cases—much lower than in non-CFTR-related vasal anomalies." (PMID 41009940, 2025). "Renal ultrasound is especially important, as men with vasal agenesis, particularly those without identifiable CFTR mutations, are at risk of concurrent renal anomalies such as unilateral renal agenesis or ectopic kidney." (PMID 41009940, 2025).
Respiratory insufficiency (4 papers, 2014 to 2023). "The main hindrances of the present CFTR modulators are related to their limitations in reducing chronic lung bacterial infection and inflammation, the main causes of pulmonary tissue damage and progressive respiratory insufficiency, particularly in adults with CF." (PMID 36902441, 2023).
Respiratory tract infection (4 papers, 2010 to 2024). An infection of the upper or lower respiratory tract. "Residual CFTR function correlates with later onset of respiratory tract infection by a wide spectrum of organisms frequently cultured from CF patients." (PMID 20932301, 2010).
spermatogenic failure (4 papers, 2017 to 2024). A male infertility characterized by dirsuption of the process of sperm development from diploid cells into mature haploid spermatozoa. "Two pathogenic variants in two patients with primary spermatogenic failure were identified: p.Lys1853*, rs748618094 in DNAH5, and p.Asp1152His, rs75541969 in CFTR." (PMID 33574797, 2020).
thalassemia (4 papers, 2013 to 2025). An inherited blood disorder characterized by a decreased synthesis of one of the polypeptide chains that form hemoglobin. "More recently, an experimental periconceptional program of CF and thalassemia screening allowed for the identification of 94% of CFTR gene mutations, with respect to 80% in the rest of Italy." (PMID 25304080, 2014).
tuberculosis (4 papers, 2020 to 2024). A chronic, recurrent infection caused by the bacterium Mycobacterium tuberculosis. "Theoretical population genetic modelling of the historical and modern exposures to tuberculosis suggests that resistance conferred by CFTR mutations may account for the modern geographic distribution and prevalence of CFTR mutations." (PMID 38952711, 2024).
abscesses (3 papers, 2019 to 2021). "Similar to macrophage-depleted embryos, ablation of CFTR was associated with a rapid and pronounced increase in cording and abscesses compared to control morphants." (PMID 34530447, 2021). "The pronounced increase in bacterial loads in CFTR-deficient animals correlates with replicating extracellular bacteria, translating into larger numbers of larvae with abscesses and with increased number of abscesses per larva in the CNS." (PMID 30759393, 2019). "Validation of Muddy plus RFB co-treatment against GD01 infection in CFTR-depleted embryos was not only reflected by a strong decrease in the pathophysiological symptoms (abscesses and cords) but also by a strong reduction in larval mortality." (PMID 34530447, 2021). "There was also a significantly greater number of embryos with abscesses and a greater number of abscesses per embryo at 4dpi in the CFTR-depleted group as compared to wild-type infections." (PMID 32850470, 2020). "Loss of CFTR increases susceptibility to M. abscessus through impaired NADPH oxidase-dependent restriction of intracellular growth, leading to uncontrolled extracellular multiplication of M. abscessus and resulting in abscess formation and lethal infection." (PMID 34530447, 2021). "Comparatively, CFTR depletion in zebrafish embryos led to remarkably improved phage responsiveness, recapitulated in improved embryo survival, reduced bacterial burdens and reduced pathophysiological signs such as cords and abscesses." (PMID 34530447, 2021). "Whereas the S form induces abscesses only rarely in wild-type (WT) fish, 30% of Mabs S-infected larvae exhibited abscesses at 3 days post-infection (dpi) in the absence of CFTR." (PMID 30759393, 2019).
anemia (3 papers, 2014 to 2021). A reduction in the number of red blood cells, the amount of hemoglobin, and/or the volume of packed red blood cells. "Nevertheless, a number of marginal protective genotype associations were also observed between specific gene mutations and anaemia (CFTR, GNAS), hyperparasitaemia (DERL3, GBP7), hyperpyrexia (GBP7, ABO) and SMA (HbS, ADCY9)." (PMID 24934404, 2014). "Some CF patients develop clinically significant anemia, suggesting that CFTR may regulate hematopoiesis." (PMID 29449653, 2018). "Given the clinical incidences of anemia in CF patients and the importance of Wnt signaling in hematopoiesis, we hypothesized that CFTR might regulate Wnt-dependent hematopoiesis through a potential interaction between Cftr and Dvl via their PDZBD/PDZ domain." (PMID 29449653, 2018). "However, some CF patients develop clinically significant anemia, suggesting that CFTR may regulate hematopoiesis." (PMID 34026749, 2021). "Given that Wnt signaling plays an important role in hematopoiesis, the presently demonstrated conserved role of CFTR in regulating Wnt signaling suggests its possible involvement in the pathogenesis of different forms of hematopoietic disorders/diseases in humans apart from anemia in CF." (PMID 29449653, 2018).
beta thalassemia (3 papers, 2013 to 2025). Beta-thalassemia (BT) is characterized by deficiency (Beta+) or absence (Beta0) of synthesis of the beta globin chains of hemoglobin (Hb). "In CF, contrary to other genetic diseases (for example beta thalassemia), the identification of carriers is possible only through molecular research of CFTR mutations." (PMID 25304080, 2014). "In order to confirm the expression of CFTR protein in the erythrocytes of patients with beta thalassemia/Hb E, western blot analysis of the erythrocyte homogenates was performed." (PMID 23383265, 2013). "We found that CFTR protein was expressed in the erythrocytes of beta thalassemia/Hb E patients." (PMID 23383265, 2013). "Our study indicates that oxidative stress induces glutathione efflux via CFTR and MRP1 in beta thalassemia/Hb E erythrocytes." (PMID 23383265, 2013). "The present study showed that GlyH-101 and MK571, inhibitors of CFTR and MRP1, respectively, reduced oxidative stress-induced senescence of beta thalassemia/Hb E erythrocytes by inhibiting glutathione efflux." (PMID 23383265, 2013). "Inhibition by GlyH-101 and MK571 of H2O2-induced glutathione efflux indicates that both CFTR and MRP1 serve as major glutathione efflux pathways under the oxidative stress in beta thalassemia/Hb E erythrocytes." (PMID 23383265, 2013).
cancers of the small intestine (3 papers, 2021 to 2024). "Interestingly, heterozygous CFTR (F508del) mutation carrier status has been recently associated with increased risk for colorectal and gallbladder/biliary tract cancer, but not with small intestinal cancer." (PMID 34274970, 2021).
chronic kidney disease (3 papers, 2017 to 2025). Impairment of the renal function secondary to chronic kidney damage persisting for three or more months. "In addition, the demonstrated aggravation of UUO-induced EMT program and renal fibrogenesis in CFTR mutant mice may explain the observation that chronic kidney diseases are commonly seen in CF patients." (PMID 28701694, 2017). "Despite all these link, the exact role of CFTR in the pathogenesis of chronic kidney diseases has never been investigated." (PMID 28701694, 2017).
co-infection (3 papers, 2009 to 2024). "In this study, we used a rat co-infection model and a wild-type and CFTR-deficient cell culture model to assess the protective effects of S. parasanguinis and nitrite." (PMID 37800950, 2023).
colon adenocarcinoma (3 papers, 2011 to 2020). "In other models, such as the colon adenocarcinoma-derived cell line T84, the same treatment reduced CFTR expression and function." (PMID 26594334, 2015). "We used the human HT-29 colon adenocarcinoma cell line because it expresses both CFTR and COMMD1 endogenously and was previously used for co-immunoprecipitation experiments." (PMID 21483833, 2011).
cystinosis (3 papers, 2017 to 2023). Cystinosis is a metabolic disease characterized by an accumulation of cystine inside the lysosomes, causing damage in different organs and tissues, particularly in the kidneys and eyes. "Nevertheless, our work suggests that CFTR correctors can be repurposed to treat cystinosis and possibly other ERAD-dependent diseases." (PMID 37561577, 2023).
endothelial dysfunction (3 papers, 2020 to 2022). In vascular diseases, endothelial dysfunction is a systemic pathological state of the endothelium (the inner lining of blood vessels) and can be broadly defined as an imbalance between vasodilating and vasoconstricting substances produced by (or acting on) the endothelium. "We next investigated if autophagy is a mechanism underlying the protective effects of CFTR against PA-induced endothelial dysfunction." (PMID 33123317, 2020). "This study is aimed at exploring the effects of CFTR on palmitate- (PA-) induced endothelial dysfunction and its underlying mechanisms." (PMID 33123317, 2020). "A large number of studies showed that CF patients had endothelial perturbation and microvascular dysfunction, suggesting that CFTR deficiency contributes to endothelial dysfunction." (PMID 33123317, 2020). "In this study, we used CFTR activator and CFTR specific siRNA to investigate the effects of CFTR on palmitate-induced endothelial dysfunction and its underlying molecular mechanisms." (PMID 33123317, 2020). "Taken together, this study demonstrates that CFTR upregulation protects against PA-induced endothelial dysfunction through improving autophagic flux with an underlying mechanism being involved in enhancing Atg12-Atg5-Atg16L complex formation and restoring the CTSB and CTSD protein expression." (PMID 33123317, 2020). "We had observed that PA significantly reduced CFTR protein expression while Forskolin restored CFTR protein expression in PA-induced endothelial dysfunction." (PMID 33123317, 2020). "CFTR agonist Forskolin upregulated CFTR protein expression and protected against PA-induced endothelial dysfunction, while CFTR knockdown exacerbated endothelial dysfunction induced by PA and blunted the protective effects of Forskolin." (PMID 33123317, 2020). "Our results showed that Forskolin significantly restored CFTR protein expression in PA-insulted endothelial cells while CFTR knockdown significantly attenuated the protective effects of Forskolin against PA-induced endothelial dysfunction." (PMID 33123317, 2020). "We thereby hypothesized that CFTR could affect FFA-induced endothelial dysfunction via the autophagy signaling pathway." (PMID 33123317, 2020). "Therefore, our findings demonstrate that CFTR upregulation by Forskolin suppresses PA-induced endothelial dysfunction." (PMID 33123317, 2020). "Whether CFTR regulated by Forskolin is involved in the protective effects of Forskolin against PA-induced endothelial dysfunction remains unclear." (PMID 33123317, 2020). "In this study, we found that CFTR expression decreased in PA-insulted endothelial cells; Forskolin significantly inhibited PA-induced endothelial dysfunction showing as increasing cell viability, inhibiting cell apoptosis, reducing ROS generation, and restoring NO generation." (PMID 33123317, 2020). "However, the role of CFTR in PAECs isolated from PAH patients is unknown and needs to be investigated to determine the contribution of CFTR in endothelial dysfunction in PAH." (PMID 35454073, 2022). "The role of CFTR in FFA-induced endothelial dysfunction remains unclear." (PMID 33123317, 2020). "Hence, we silenced CFTR expression to further determine whether downregulation of CFTR participated in PA-induced endothelial dysfunction." (PMID 33123317, 2020).
Hypercholesterolemia (3 papers, 2015 to 2017). An increased concentration of cholesterol in the blood. "In this context, our laboratory workflow is able to analyze BRCA1/2, CFTR, and familiar hypercholesterolemia genes in the same 454 Junior run." (PMID 25922769, 2015).
hypertriglyceridemia (3 papers, 2010 to 2023). A laboratory test result indicating elevated triglyceride concentration in the blood. "Changes in intestinal FA metabolism related to defective CFTR may have deleterious health consequences for CF patients and may explain certain aberrations in plasma saturated and n-7 FA and pathophysiological manifestations such as hypertriglyceridemia." (PMID 20463919, 2010).
hypogonadotropic hypogonadism (3 papers, 2018 to 2022). Abnormal ovarian or testicular function due to insufficient hormonal stimulation from the hypothalamic-pituitary axis. "In conclusion, the high incidence of abnormal epididymides in patients with HIR may stem from a combination of a degree of prepubertal hypogonadotropic hypogonadism, insufficient CFTR activity, and FGFR1 deficiency." (PMID 35725394, 2022).
hypothyroidism (3 papers, 2015 to 2025). Abnormally low levels of thyroid hormone. "Within this context, Li and coauthors suggested that the increased Na+ absorption due to CFTR−/− may contribute to hypothyroidism on CF patients." (PMID 29376041, 2017).
idiopathic bronchiectasis (3 papers, 2008 to 2026). Idiopathic bronchiectasis (IB) is a progressive lung disease characterized by chronic dilation of the bronchi and destruction of the bronchial walls in the absence of any underlying cause (such as post infectious disease, aspiration, immunodeficiency, congenital abnormalities and ciliary anomalies). "To date, a combination of one ENaC mutation, including this p.Ser82Cys mutation, plus a CFTR mutation, has been occasionally reported in patients with idiopathic bronchiectasis." (PMID 18507830, 2008).
idiopathic pulmonary fibrosis (3 papers, 2020 to 2025). Idiopathic pulmonary fibrosis (IPF) is a nonneoplastic pulmonary disease that is characterized by the formation of scar tissue within the lungs in the absence of any known cause. "We have shown that TGF-β1 inhibits CFTR mRNA in human bronchial epithelial cells from COPD and idiopathic pulmonary fibrosis (IPF) lungs." (PMID 32481719, 2020).
Kidney Cyst (3 papers, 2015 to 2024). Abnormal fluid filled sac within the kidney, either acquired or congenital. "The in vivo mechanisms involved in the activation of CFTR during kidney cyst inflation are still emerging." (PMID 34445719, 2021). "Mirroring kidney cysts, the KV lumen inflation is dependent on CFTR activity and, as we clearly show, the knockdown of Polycystin-2 results in larger KV lumens through overstimulation of CFTR." (PMID 26432887, 2015). "Taken all together, we propose that as in kidney cysts, in KV cells the drop of the intracellular Ca2+ levels caused by the knockdown of Polycystin-2, leads to the activation of AC5 and AC6 and to the inhibition of PDE1A, raising the levels of cAMP and, thus, activating CFTR." (PMID 26432887, 2015).